E2F1 (E2F transcription factor 1)
Diseases named in the same sentence as E2F1 in open-access papers (continued):
Sharing a sentence is not in itself a finding about the gene and the disease.
cancer (continued). "Further analysis found a positive correlation of TLS gene expression with E2F1 expression when the cell lines from the cancer cell line encyclopedia." (PMID 36266721, 2022). "Lysine-specific demethylase 5A (KDM5A) which is participated in human cancer has been inhibited through binding of NEAT1 to the E2F transcription factor 1 (E2F1) protein." (PMID 35676702, 2022). "Transcription of ESRP1, which requires the binding of E2F1, is elevated in many cancer types, but is drastically lowered in cancer cells within hypoxic niches, with the concomitant induction of EMT." (PMID 35158828, 2022). "A high-throughput Co-IP-mass spectrometry approach to screen for E2F1:coregulator interactions in metastatic cells of various cancer types was employed." (PMID 36678712, 2022). "With such conspicuous roles of both KAT2A and E2F1 in cellular functions and putative links to cancer, we investigated the common molecular mechanisms and potential transcription target of their interaction across pan-cancer." (PMID 36292703, 2022). "As for pathways in cancer, specifically in the cell cycle, the transcription factor E2F1 and the tumor suppressor protein retinoblastoma (RB) are two key factors that regulate the progression of the cell cycle." (PMID 33757543, 2021). "As one of the most investigated E2F families in cancer, E2F1 was originally recognized as an important regulator of the cell cycle." (PMID 33986804, 2021). "To explore the transcription levels of CCNE1, E2F1 in other types of cancer, we profiled the tissue-wise expression of these genes in different cancer types by GEPIA 2 based on TCGA datasets." (PMID 33613291, 2021). "miR‐205‐5p and miR‐342‐3p synergistically inhibit the transcription factor E2F1 to reduce anti‐cancer chemotherapy resistance." (PMID 34428336, 2021). "Some studies have shown that lncRNAs are involved in regulation of the miRNA/E2F1 axis in malignant tumours." (PMID 33436941, 2021). "Much work thus far has shown that the elevated expression of E2F1 can lead to the abnormal growth of cells and that it can participate in the occurrence and development of malignant tumors." (PMID 34564711, 2021). "E2F1 is a potent transcription regulator that participates in the development of many different types of cancer, and a previous paper reported that E2F1 is also involved in ccRCC progression." (PMID 33468140, 2021). "Several investigations reported that overexpression of E2F1 had clinical relevance in various types of cancers." (PMID 34252883, 2021). "Previous studies have shown that E2F1 is an oncogene that can promote the occurrence and development of malignant tumours, such as breastcancer." (PMID 33436941, 2021). "FOXM1, E2F1, and WEE1 have been implicated in the pathogenesis of human cancers, yet their roles remain vague in STS." (PMID 33564073, 2021). "Second, we measure the miR-185-3p transcriptional target, E2F1 mRNA, in a prospective multidisciplinary study, in relation to cancer subtypes, stage, and grade, in order to link obtained results with the clinicopathological features and the clinical outcome." (PMID 34745973, 2021). "A previous study has shown that PRMT5 directly methylated E2F1 and regulates the cell cycle, which is required for gating the function of E2F1, suggesting that E2F1 methylation by PRMT5 leads to cancer cell cycle progression." (PMID 33495409, 2021). "Collectively, these results demonstrate that E2F1 along with genomic amplification are responsible for the upregulation of PLANE in cancer cells." (PMID 34145290, 2021). "Further, the downstream E2F1 pathway is well-established as oncogenic, as it promotes the growth and metastasis of multiple cancer types." (PMID 33468140, 2021). "E2F1, a member of the E2F-family activator subcategory, plays a crucial role in cancer cell proliferation, invasion, and apoptosis." (PMID 34966670, 2021).
cancer (continued). "This is also consistent with the motif enrichment result that enriched TFs in the PRC2−-CGI class were strongly overlapped between different cancer types, and were associated with cell-cycle TFs, such as SP1, JUND, NFY, E2F4, and E2F1." (PMID 33931649, 2021). "E2F1, as a member of the E2F family, is an essential transcription factor, which involves in the regulation of multiple biological processes of cancers, including cell cycle, programmed cell death, DNA damage, and self-renew of cells." (PMID 34079762, 2021). "It is well known that E2F1 is overexpressed in several cancers, including NSCLC36–38 and that an aberrant E2F1 expression is correlated with a lower overall survival of NSCLC patients." (PMID 33883577, 2021). "While overexpression of E2F1 induces senescence in normal cells, suppression of E2F1 triggers senescence in cancer and immortalized cells, indicating the complexity of the regulation of cellular senescence by E2F1." (PMID 34707111, 2021). "E2F1 was significantly high expressed (log2FC > 1, q < 0.01) in 22 of 31 cancer types in TCGA data set." (PMID 33613291, 2021). "miR-106a-5p and miR-372-5p was bound to E2F1 to reduce cancer progression by inhibiting the expression of E2F1." (PMID 33868788, 2021). "Transgenic mice overexpressing E2F1 were found to be more susceptible to tumorigenesis due to the loss of normal regulation of the cell cycle, further suggesting the oncogenic role of E2F1 in cancer." (PMID 33986804, 2021). "LIM and cysteine-rich domains 1 (LMCD1) had been found acting as an activator E2F1 transcription factor in human cells but its role in cancers were rarely investigated." (PMID 33682883, 2021). "The increased expression of E2F1 is conserved in almost all cancers, indicating a similar role of E2F1 in these cancers from an evolutionary point of view." (PMID 34650921, 2021). "Previous studies have reported that the aberrant expression of Timeless in cancer is activated byERK signaling pathways, or by transcription factors such as E2F1 and E2F4." (PMID 33971927, 2021). "The 11 TFs were highly expressed in most cancers, with E2F1 showing the most significant upregulation." (PMID 34859058, 2021). "Total E2F reduction induces senescence-like cell cycle arrest in cancer cells; particularly, E2F1 blocks cell proliferation." (PMID 34856941, 2021). "Functional network analysis suggested that H2AFZ mainly regulates cell cycle signaling and DNA replication via pathways involving several cancer-related kinases and transcription factor E2F1." (PMID 34760688, 2021). "Here we functionally characterise a non-protein product of the 3q region, the long noncoding RNA (lncRNA) PLANE, which is upregulated in diverse cancer types through copy number gain as well as E2F1-mediated transcriptional activation." (PMID 34145290, 2021). "Despite a clear link between dysregulated E2F1 activity and cancer progression, literature on the contribution of E2F1 to DNA replication stress phenotypes is somewhat scarce." (PMID 33665206, 2020). "This review summarizes the role of the archetypal member of the E2F family – namely E2F1 – in the DNA replication stress pathway and highlights its dysregulation in cancer." (PMID 33665206, 2020).
cancer (continued). "Abnormalities in expression and amplification of some important CCP-related genes or regulators such as cyclin D1, E1, and E2F1 were frequently observed in various cancer types." (PMID 32370292, 2020). "It is a consensus that the carcinogenic effects of E2F1 and c-Myc, and E2F1 is expressed in a variety of cancers." (PMID 32917956, 2020). "We also analyzed the relationship between E2F1 and DDX11 expression in TCGA database and found that E2F1 expression was positively correlated with DDX11 expression in these cancers." (PMID 32332880, 2020). "E2F1 is a positive regulator of cell cycle, and is up-regulated in various aggressive (rapidly-dividing) cancer cells." (PMID 32930631, 2020). "Several studies have reported the reciprocal relationship between KLF15 expression and cell cycle regulators, such as E2F1 and cyclin-cdk inhibitors p21Cip1/p57kip2, in different types of cancer." (PMID 32850313, 2020). "In agreement with decreased mRNA abundance, E2F1 protein expression was substantially reduced in all tested cancer cell lines upon IGF2BP1 depletion." (PMID 32761127, 2020). "ICAT has been reported to be a direct target of E2F1 that is responsible for the suppression of β-catenin activity in cancer cells." (PMID 32326181, 2020). "After assessing the diagnosis and prognostic values of identified key regulators in both the TCGA and GEO verification datasets, CXCL8, CYP2C8, and E2F1 were selected, which were reported as potential biomarkers in some cancers." (PMID 32851080, 2020). "Here, we show that the aberrant activation of E2F1 found in several types of cancer can be alleviated by inactivating PARP1." (PMID 33050515, 2020). "E2F1, a member of the E2F transcription factor family, controls networks of increasing importance in the context of cancer progression." (PMID 32863950, 2020). "Several studies have shown that E2F1 has potential for mediating multiple cancer hallmarks, such as sustaining proliferative signaling, metabolic reprogramming, and tissue invasion and metastasis." (PMID 32812032, 2020). "Further, hyper-proliferation effects in cancer have been directly ascribed to E2F1 dysregulation, and E2F pro-apoptotic activity is mainly attributed to E2F1." (PMID 33665206, 2020). "E2F1, a key regulator for the G1/S phase transition in the E2F family, was found to be dysregulated in a variety of cancers, including GC." (PMID 32767629, 2020). "Here, we reveal that IGF2BP1 stabilizes E2F1–3 mRNAs leading to enhanced E2F-driven gene expression and cell cycle progression in cancer cells." (PMID 32761127, 2020). "Studies have shown that E2F1 can play different roles in tumor suppressor genes or oncogenes in different cancers." (PMID 33604289, 2020). "The cdk4, cdk6, rb1, and e2f1 genes are expressed in a wide range of cancers according to analysis of the TCGA PANCAN database, which is composed of 12,839 samples." (PMID 32357912, 2020). "Based on these findings, we provide new functional and mechanistic insights on the effect of E2F1-regulated lncRNAs in cancer metabolism." (PMID 32863950, 2020). "Inactivation of RB1 expression in cancer leads to the deregulated activity of the transcription of E2F1, E2F2, and E2F3." (PMID 32429447, 2020). "It has become increasingly clear that E2F1, through complex functions via the p73/DNp73-miR205 axis, is both involved in regulating drug resistance and cancer progression as a genotoxic-treatment induced apoptosis, with context-dependent effects." (PMID 32429253, 2020). "E2F1 is defined as a transcription activator and reported to regulate cell cycle, cell growth, and metastasis in cancers." (PMID 31934717, 2020). "Enforced E2F1 expression in advanced tumors and metastases of different types of cancers correlates with pronounced resistance toward therapy and poor patient prognosis." (PMID 32001707, 2020).
cancer (continued). "We showed that SLC16A1-AS1 forms an RNA-protein complex with its own transcription factor E2F1 to promote cancer metabolic reprograming and an invasive phenotype." (PMID 32863950, 2020). "The results from our study shed light on the important role which E2F1 undertakes in mediating the cancer-relevant effects of PRMT5." (PMID 32709847, 2020). "Our results indicate that MCT1 is inevitably co-transcribed and -expressed with the mitochondrial respiration activator SLC16A1-AS1 in a high-E2F1 cancer cell context." (PMID 32863950, 2020). "The transcription factor E2F1 is involved in DNA repair and replication in multiple cancer types and an “addiction” to this oncogene is often present." (PMID 33396205, 2020). "Among the E2F family, E2F1 is the most thoroughly studied transcription factor in human malignancies, which exerts important effect in regulating cancer progression." (PMID 32351327, 2020). "In this study, we demonstrated that transcription factors E2F1 and c-Myc upregulated the progression and metastatic ability of cancer." (PMID 32917956, 2020). "miR-17-5p and E2F1 have been described as deregulated in cancer, but they have scarcely been studied in pituitary neuroendocrine tumours (PitNETs)." (PMID 32316225, 2020). "Several genes in A3 1–31 Mb significantly enriched pathways in cancer including the transcription factor E2F1 recently identified as a key regulator of a set of metastasis promoter genes in HBCs56." (PMID 31969654, 2020). "E2F1 is implicated in regulating Zeb1 and Zeb2 expression, which promotes EMT, and MMP9, which drives cancer cell invasion." (PMID 32224870, 2020). "Our data underscore that, beyond its well-known role in controlling cell cycle, E2F1 reprograms cancer metabolism to support metastatic characteristics." (PMID 32863950, 2020). "MDM2 binds and degrades Rb directly, thereby inhibiting the Rb-E2F1 interaction and promoting transcription of E2F1 to drive cancer cell proliferation." (PMID 32560270, 2020). "NR4A1 is found to be overexpressed in numerous cancers, leading to increased proliferation and survival in these cancer cells via upregulating some target genes, including cyclin D2, E2F1, and survivin." (PMID 33328994, 2020). "Cyclin E can be regulated independently of E2F1 as well: cyclin E overexpression, a common event in cancer, can arise from its defective proteolysis through inactivating mutations in its E3 ubiquitin ligase Fbxw7." (PMID 33665206, 2020). "We surveyed the direct neighbors (containing 12111 nodes) of the module E2F1 (module boundary); of them, 1496 were specified as cancer-related genes (coverage = 0.78)." (PMID 32193399, 2020). "Of these, TFs AP2 alpha, AP2 gamma are known to be upregulated in carcinoma and E2F1 is a known regulator of keratinocyte proliferation." (PMID 32079144, 2020). "We analyzed the expression of cell proliferation-, cell cycle-, and cancer-related proteins, including E2F1, Ki-67, and Cy19, Cox-2." (PMID 30943209, 2019). "Understanding the molecular mechanisms responsible for regulating the diverse biological outcomes of E2F1 activity remains a central question in E2F biology which, further, has direct relevance to its pathological role in cancer." (PMID 31249870, 2019).
cancer (continued). "The uncovered mutual regulation between Cip2a and miR-301a points toward new prognostic and therapeutic options by using components of the Cip2a/E2F1/miR-301a/ERK loop as potential key targets to restrict cancer progression of TNBC." (PMID 31762806, 2019). "GATA is an important transcription factor involved in cancer cell growth, and E2F1 plays a crucial role in controlling the cell cycle." (PMID 31040909, 2019). "Upregulation of miR-17 can promote cancer growth via aiming E2F1 and increase angiogenesis through thrombospondin-1." (PMID 31032345, 2019). "This global approach further highlighted strong correlations between A3B and expression of E2F1, E2F2, E2F7, and E2F8 and indicated that the association between A3B, this signal transduction pathway, and the cell cycle is evident in many cancer types." (PMID 30723127, 2019). "The expression levels of several cell proliferation- including E2F1, Ki-67 and Cy-19, and Cox-2 (an essential regulator of the G2/M transition) as cancer-related makers, were upregulated, especially in NDMA + ESP-treated cells." (PMID 30943209, 2019). "E2F1 has been shown sto exhibit dual properties and can act as a tumor suppressor or oncogene in the same cancer." (PMID 30967995, 2019). "E2F1 regulates the cell cycle and is involved in cancer genesis, and the GFi-1 protein regulates hematopoiesis and oncogenesis." (PMID 31040909, 2019). "As glucose is the main nutritional source for the maintenance of cancer cells growth, we investigated the importance of glucose for mTORC1 activation under E2F1 oncogenic signaling." (PMID 31627130, 2019). "Taken together, these observations strongly suggest that the increase in MED28 expression by E2F-1, ETS-1, C/EBPβ, and NRF-1 is associated with cancer progression and poor prognosis." (PMID 30970566, 2019). "Despite many years of investigation, the role of E2F1 in regulating the fate of normal cells and cancer cells remains controversial." (PMID 31866820, 2019). "Recent research uncovered an additional function of E2F1; under the influence of certain cofactors, E2F1 activates the growth receptor signaling pathways, resulting in cancer progression and chemo resistance." (PMID 31598149, 2019). "MiR-149 is reported to be a pro-apoptotic miRNA, which can inhibit the expression of Akt1 and E2F1 and thus induce cancer cell lines apoptosis." (PMID 30619739, 2018). "The upregulation of lncRNAs in cancer is associated with increased activities of oncogenic transcription factors such as c-Myc, SP1 and E2F1." (PMID 29416741, 2018). "Data herein indicate that PARP‐1 positively regulates E2F1‐mediated HR gene expression in cancer, and that suppression of this activity can potentially induce a “BRCA‐ness” phenotype." (PMID 30467127, 2018). "In this case, the challenge is to understand what biological pathways can be directly regulated by E2F1, what are the possible direct and indirect feedbacks to the regulation of E2F1 itself and how they are changing in cancer progression." (PMID 29370181, 2018). "Several of the predicted targets are known to be involved in cancer progression (E2F1, E2F5, ERBB, PTEN), invasion and metastasis (ZEB1/2, LRP-1)." (PMID 30510566, 2018). "Dysregulation of E2F1 is a frequent event observed in human cancer cells because of the inactivation of the retinoblastoma protein RB1, altered expression of cyclin-dependent kinases or their inhibitors and/or the expression of transforming viral proteins." (PMID 30359437, 2018). "Among all the E2F family members E2F1 has been the most researched and investigated member in human cancers." (PMID 30487158, 2018).